ZNF132 (zinc finger protein 132)
Description:
May be involved in transcriptional regulation.
Synonyms: pHZ-12
Tractability: PROTAC: ubiquitination databases record sites on it.
Gene: Protein-coding gene on chromosome 19 (58,432,814 to 58,440,153, reverse strand). Ensembl gene ENSG00000131849.
Subcellular location: Nucleus
Subcellular location (Human Protein Atlas): Vesicles; Intermediate filaments
Gene Ontology:
Molecular function: DNA-binding transcription factor activity, RNA polymerase II-specific; RNA polymerase II cis-regulatory region sequence-specific DNA binding
Biological process: regulation of transcription by RNA polymerase II; negative regulation of transcription by RNA polymerase II; regulation of DNA-templated transcription
Cellular component: nucleus
Genetic constraint (gnomAD): Loss-of-function variants: 6 observed, 8.19 expected, observed/expected ratio (o/e) 0.73, 90% interval 0.4 to 1.43. That is too few expected variants to judge how well the gene tolerates losing a copy. Missense variants: 816 observed, 801.85 expected, observed/expected ratio (o/e) 1.02, 90% interval 0.96 to 1.08. Synonymous variants: 265 observed, 277.33 expected, observed/expected ratio (o/e) 0.96, 90% interval 0.86 to 1.06.
Homologues: Orthologues: chimpanzee ZNF132 (99% identical), macaque ZNF132 (95% identical), dog ZNF132 (76% identical), tropical clawed frog znf684 (16% identical). Paralogues in human: ZNF658 (41% identical), ZNF16 (40% identical), ZNF585B (40% identical), ZNF41 (40% identical), ZNF484 (40% identical), ZNF605 (39% identical), ZNF33B (39% identical), ZNF189 (38% identical), ZNF227 (38% identical), ZNF470 (38% identical), ZNF7 (38% identical), ZNF226 (37% identical), and 164 more.
Diseases named in the same sentence as ZNF132 in open-access papers:
ZNF132 is named in the same sentence as 26 diseases in open-access papers, as found by Europe PMC text mining. Sharing a sentence is not in itself a finding about the gene and the disease. The quoted sentences say what the papers report.
breast carcinoma (7 papers, 2015 to 2025). "miR-21 is an established oncogenic miRNA exerting its suppressive activities on key tumor suppressive targets such as StAR Related Lipid Transfer Domain Containing 13 (STARD13) and Zinc Finger Protein 132 (ZNF132) as implicated in breast cancer." (PMID 40863728, 2025). "ZNF132 is implicated as a master transcriptional regulator of networks that underlie the breast cancer phenotype." (PMID 34797887, 2021). "In the case of ZNF132, it was observed to be downregulated in prostate cancer, breast cancer and esophageal squamous cell carcinomas." (PMID 37254212, 2023). "The protein levels of ZNF132 in breast cancer cell lines and normal breast epithelial cell line MCF-10A were examined." (PMID 33827486, 2021). "Previous studies have identified the DNA methylation alterations of ZNF132 in breast cancer, esophageal squamous cell carcinoma (ESCC), oropharyngeal squamous cell carcinoma, and prostate cancer." (PMID 34778269, 2021). "However, in analysis of breast cancer datasets, ZNF132 has been identified by computational approaches as a potential transcriptional master regulator of several transcriptional processes that are well-known hallmarks of cancer." (PMID 37254212, 2023). "ZNF132 methylation was detected in a panel of breast cancer cell lines using MSP assay." (PMID 33827486, 2021). "Finally, MSP analysis demonstrated that ZNF132 was hypermethylated in a panel of breast cancer cell lines and 5-aza-2′-deoxycytidine (5-Aza-dC) treatment restored ZNF132 expression in partial cell lines." (PMID 33827486, 2021). "As for znf132, methylation mediated silencing events have been validated in esophageal squamous cell carcinoma and breast cancer, however, not in colon cancer." (PMID 33892797, 2021).
esophageal squamous cell carcinoma (7 papers, 2018 to 2023). Esophageal squamous cell carcinoma (ESCC) is a type of esophageal carcinoma (EC) that can affect any part of the esophagus, but is usually located in the upper or middle third. "Low expression of ZNF132 has been reported in cancer and is associated with the cell growth, migration and invasiona ablity in prostate cancer and esophageal squamous cell carcinoma up to date." (PMID 33827486, 2021). "Zinc finger protein 132 (ZNF132) is downregulated by promoter methylation in prostate cancer and esophageal squamous cell carcinoma." (PMID 33827486, 2021). "Through interfering with the recruitment of SP1 to ZNF132 promoter region, methylation of SP1-binding site can inhibit ZNF132 transcriptional expression to impact the tumor in the development of esophageal squamous cell carcinoma." (PMID 33522959, 2021). "For example, ZNF132 was shown to be epigenetically silenced via promoter hypermethylation in HNSCC, esophageal squamous cell carcinoma (ESCC), and lung adenocarcinoma (LUAD)." (PMID 36547193, 2022).
prostate carcinoma (6 papers, 2018 to 2023). A carcinoma that arises from epithelial cells of the prostate gland. "In the case of ZNF132, low protein expression was associated with a higher Gleason score and advanced T stage in prostate cancer patients, indicating more a aggressive and progressive disease phenotype." (PMID 37254212, 2023). "ZNF132 has been reported to be downregulated due to abnormally hypermethylation in prostate cancer and lung cancer, and this is related to the prognosis of cancer." (PMID 35634444, 2022). "Silencing of the transcription factor ZNF132 promotes progression in ESCC; and its downregulation is associated with poor prognosis in prostate cancer, indicating tumor suppressive properties." (PMID 34797887, 2021). "Consistent with our study in ESCC patients, their results also illustrate that ZNF132 have the potential to be a new candidate methylation marker for prostate cancer." (PMID 30578410, 2018). "There are not many studies on the biological function of ZNF132; however, decreased expression of ZNF132 has been reported in prostate cancer and is associated with aggressive prostate cancers." (PMID 30578410, 2018).
lung adenocarcinoma (2 papers, 2022 to 2023). A carcinoma that arises from the lung and is characterized by the presence of malignant glandular epithelial cells. "Low ZNF154 and low ZNF132 expression were associated with shorter overall survival in both head and neck squamous cell carcinoma (HNSCC) and lung adenocarcinoma (LUAC patients)." (PMID 37254212, 2023). "The prognostic value of ZNF154 and ZNF132 expression was similarly observed in patients from the lung adenocarcinoma (LUAD) TCGA patient cohort." (PMID 37254212, 2023).
lung carcinoma (2 papers, 2022). "We reported the first clinical evidence that methylation of DRD4, ZNF132 and ZNF43t may be also involved in lung cancer development." (PMID 35313869, 2022). "Besides, DRD4, ZNF132 and ZNF43 have been linked with other non-lung cancer types: DRD4, encoding dopamine receptor, is involved in early brain development and epigenetically repressed in pediatric CNS tumors; it also has be identified as a potential epidriver in hepatocellular carcinoma." (PMID 35313869, 2022).
oropharyngeal squamous cell carcinoma (2 papers, 2019 to 2021). "A cluster of Krüppel-type zinc finger protein genes (including ZNF132 and ZSCAN18, earlier known as ZNF447) on chromosome 19q13 was earlier found significantly epigenetically downregulated in oropharyngeal squamous cell carcinoma." (PMID 31796082, 2019).
autism (1 paper, 2020). Persistent deficits in social interaction and communication and interaction as well as a markedly restricted repertoire of activity and interest as well as repetitive patterns of behavior. "It has been also reported that autism gene CHD8 modifies the expression of ZNF132." (PMID 31455857, 2020). "ZNF132 is expressed highly in the cerebellum, and a recent study has found that cerebellum can regulate social behavior by controlling dopamine release, suggesting that this may contribute to mental disorders, such as autism and schizophrenia." (PMID 31455857, 2020).
head and neck cancer (1 paper, 2023). A primary or metastatic malignant neoplasm affecting the head and neck. "We examined prognostic significance of ZNF154 and ZNF132 expression and DNA methylation in independent patient cohort of about 500 head and neck cancer patients in the Cancer Genome Atlas (TCGA)." (PMID 37254212, 2023). "Both ZNF132 and ZNF154 represent novel clinically significant biomarkers in head and neck cancer with potential tumour suppressive properties." (PMID 37254212, 2023). "The epigenetic silencing of ZNF154 and ZNF132 were not confined to head and neck cancers." (PMID 37254212, 2023).
oral cancer (1 paper, 2023). "First, it was not possible to express a full length ZNF154 or ZNF132 construct within oral cancer UM-SCC-1 cells in order to identify possible downstream targets of these proteins in the cancer cell environment." (PMID 37254212, 2023).
tumor (11 papers, 2015 to 2025). "The analysis showed that high methylation levels of ZNF132 were associated with older age and advanced tumor stage in BC patients as compared to low methylation group." (PMID 33827486, 2021). "Our results suggest that ZNF132 plays an important role in the development of ESCC as a tumor suppressor gene and support the underlying mechanism caused by the DNA hypermethylation-mediated Sp1-binding decay and gene silencing." (PMID 30578410, 2018). "The results showed that the promoter methylation levels of ZNF671 and ZNF132 were significantly higher in CRC tumor tissues compared to normal mucosa." (PMID 40791581, 2025). "Gene enrichment analysis of tumor samples with high ZNF132 and ZNF671 methylation revealed their involvement in immune pathways and cell proliferation, highlighting their biological functions and potential prognostic value." (PMID 40791581, 2025). "The enriched pathways included signal transduction, cell adhesion, immune regulation, metabolism, and disease development, underscoring the roles of ZNF671 and ZNF132 in tumor progression and prognosis." (PMID 40791581, 2025). "This reduced gene expression in primary tumors was also observed for ZNF132 (tumour 26.38 ± 122.76 versus non-tumour 88.89 ± 43.65, p < 0.001)." (PMID 37254212, 2023). "Consistent with their roles as tumor suppressors, we found that low expression of either ZNF154 or ZNF132 were significantly associated with a worse overall survival in 508 HNSCC patients." (PMID 37254212, 2023). "And in the case of ZNF132, patients whose primary tumours expressed low levels of ZNF132 (n = 162, 33%) showed a significantly decreased overall survival when compared to the remaining cohort (Log-rank, p < 0.05)." (PMID 37254212, 2023). "In conclusion, aberrant hypermethylation of ZNF154 and ZNF132 mediated their silencing in primary HNSCC tumor tissue samples." (PMID 37254212, 2023). "Chi-square test showed that the expression of ZNF132 was significantly associated with HER2 status (P = 0.001), ER status (P = 0.000), PR status (P = 0.000), tumor size (P = 0.006) and lymph node metastasis (P = 0.003)." (PMID 33827486, 2021). "It is inversely correlated with STARD13, ZNF132 and MAT2A, which are implicated in tumor development." (PMID 34797887, 2021). "We further examined the protein expression level of ZNF132 in tumor tissues by Western blotting, and found that ZNF132 was expressed in a subcutaneous injection of ZNF132 stable cell line." (PMID 30578410, 2018). "Our study is the first one to show both in vitro and in vivo the tumor suppression function of ZNF132, indicating the pathological importance of reducing ZNF132 expression by hypermethylation of its promoter region." (PMID 30578410, 2018). "Most importantly, the methylation status of ZNF132 promoter in the tumor tissues of ESCC patients is an independent prognostic factor, and has the potential use as a biomarker useful in prognosis of ESCC." (PMID 30578410, 2018). "The xenograft study suggests that ZNF132 plays a role as tumor suppressor gene in preventing ESCC in vivo." (PMID 30578410, 2018). "As methylation of gene promoter regions is a well-known gene expression regulation mechanism, we first examined the expression of ZNF132 in 91 pairs of tumor and adjacent control tissues from ESCC patients." (PMID 30578410, 2018). "Methylation of Sp1-binding site prevents the transcriptional activator Sp1 from binding to ZNF132 promoter, silencing ZNF132 tumor suppressor gene." (PMID 30578410, 2018). "For instance, in LSCC we observed four TFs (HOXA4, HOXA5, TAL1, ZNF132) undergoing promoter hypermethylation in at least 50 % of the LSCC tumour samples where these TFs were underexpressed." (PMID 27562343, 2016). "In spite of the fact that the HNSCC cell line produced truncated ZNF154 and ZNF132 proteins, we wanted to examine what effects these partial proteins might have on tumor cell phenotype." (PMID 37254212, 2023).
tumor (continued). "This implied that ZNF132 can serve as a tumor suppressor in BC." (PMID 33827486, 2021). "To investigate whether ZNF132 gene functions as a tumor suppressor also in vivo, we established the xenograft model." (PMID 30578410, 2018). "In ESCC tumor tissue, the ZNF132 gene is hypermethylated in its promoter region." (PMID 30578410, 2018). "In 20 patients from the TCGA cohort of HNSCC patients where ZNF154 and ZNF132 DNA methylation and RNA expression could be compared in tumor and adjacent normal tissue, there was increased DNA methylation and decreased expression of both ZNF154 and ZNF132 in primary tumours." (PMID 37254212, 2023). "Analyzing the methylation levels of ZNF132 and ZNF671 and their impact on gene expression in CRC patient samples helps clarify the roles of these biomarkers in tumor development and progression." (PMID 40791581, 2025). "Based on the TCGA database, we found that high methylation of ZNF132 and ZNF671 results in gene silencing or reduced expression, which in turn influences the tumor progression and correlates with the prognosis of CRC patients." (PMID 40791581, 2025). "Further analysis using WGCNA and xCell to explore the correlation between ZNF132 and ZNF671 expression and immune cell infiltration in the TME indicated that both genes are involved in regulating immune responses and tumor-stroma interactions." (PMID 40791581, 2025). "In this current study, we found in genomic datasets obtained from the TCGA that both ZNF154 and ZNF132 were silenced and hypermethylated in a significant number of HNSCC primary tumour samples when compared to adjacent non-tumor samples from the same patient." (PMID 37254212, 2023). "Based on the UALCAN database, we observed a significant downregulation of ZFP28, ZNF132, ZNF418, ZNF426, ZNF540, and ZNF880 expression levels in primary tumor tissues compared to normal tissues." (PMID 36547193, 2022). "ZNF132 belongs to C2H2 zinc finger protein family and plays an important role in ESCC development as a tumor suppressor gene." (PMID 35313869, 2022). "Among the most significantly downregulated targets were MAT2A and the tumor suppressive genes STARD13 and ZNF132." (PMID 34797887, 2021). "In summary, both ZNF132 and ZNF671 may play crucial roles in regulating immune responses and tumor-stroma interactions." (PMID 40791581, 2025). "Unfortunately, ZNF154 and ZNF132 expression data was not available for 30 non-tumour tissue samples, so those samples were excluded from our analysis." (PMID 37254212, 2023). "In this study, we show that ZNF132 gene is silenced in ESCC tumor tissues, but not in adjacent control tissues in paired tissue samples from ESCC patients." (PMID 30578410, 2018). "Not all HNSCC tumours showed epigenetic silencing of ZNF154 or ZNF132 expression." (PMID 37254212, 2023). "Likewise, none of the Epi‐LumB specific markers, i.e. ZNF132, TTBK1 and KCNA3 have been described as tumor suppressors and it is not clear at this point whether epigenetic inactivation of these genes represent driver events that contribute to cancer development." (PMID 25468711, 2015).
cancer (9 papers, 2015 to 2025). A tumor composed of atypical neoplastic, often pleomorphic cells that invade other tissues. "Further analysis across various cancers showed that ZNF132 and ZNF671 expression was significantly correlated with immune cell infiltration." (PMID 40791581, 2025). "Among the genes in the ZNF132 node, CBX7 is implicated in cancer progression and EMT, PTPRN2 confers resistance to apoptosis, and NTRK3 is a receptor tyrosine kinase whose overactive kinase domain is implicated in growth and metastasis." (PMID 34797887, 2021). "In the present study, the expression of ZNF132 mRNA and protein level was determined based on the Cancer Genome Atlas (TCGA) RNA-Seq database and clinical samples analysis and multiple cancer cell lines verification." (PMID 33827486, 2021). "The fact that epigenetic treatment modulates ZNF132 expression shows its potential as an epigenetic cancer therapy." (PMID 30578410, 2018). "Meanwhile, ZNF132 gene silencing mediated by hypermethylation was confirmed in both solid tissues and cancer cell lines." (PMID 30578410, 2018). "Besides, methylation of DRD4, ZNF132 and ZNF43 have been reported to play roles in other cancer types." (PMID 35313869, 2022). "While we were able to express full-length ZNF154 and ZNF132 constructs in HEK-293 cells without issue, attempts to express these same constructs in head and neck UM-SCC-1 cancer cells resulted in truncated proteins lacking partial internal amino acid sequences." (PMID 37254212, 2023).
ZNF132 also shares sentences with these, for which no sentence is quoted: colon cancer (2 papers); glioma (2); adenocarcinoma (1); adenoma (1); CNS tumors (1); colorectal cancer (1); esophagus cancer (1); head and neck squamous cell carcinoma (1); hepatocellular carcinoma (1); leukemia (1); liver cancer (1); lymph node metastasis (1); mental disorder (1); schizophrenia (1); uveal melanoma (1).